TLR9 (toll like receptor 9)
Diseases named in the same sentence as TLR9 in open-access papers (continued):
Sharing a sentence is not in itself a finding about the gene and the disease.
cancer (279 papers, 2005 to 2026). A tumor composed of atypical neoplastic, often pleomorphic cells that invade other tissues. "Toll-like receptor 9 (TLR9) activation causes antitumour activity by interfering with cancer proliferation and angiogenesis." (PMID 34663410, 2021). "Similar to TLR3 and TLR7, TLR9 is expressed on endosomal membranes of several immune cells, and it has been linked to acute pancreatitis and cancer." (PMID 34884547, 2021). "Polymorphisms in the TLR9 gene and promoter region including TLR9 1635A/G and 1486C/T have been found to be associated with multiple infectious diseases and cancers." (PMID 30651082, 2019). "In carcinomas associated with Merkel cell polyomavirus infection, virus presence also correlates with a strong decrease in TLR9 expression." (PMID 29472602, 2018). "In cancer, expression and stimulation of TLR9 is linked with invasiveness, as shown in in vitro experiments." (PMID 29225688, 2017). "As recently demonstrated, TLR9 expression in cancer cells is upregulated in response to genotoxic stress caused by irradiation or chemotherapy." (PMID 26046794, 2015). "Cancer cells can also upregulate TLR9 in response to genotoxic stress caused by irradiation or chemotherapy." (PMID 26046794, 2015). "Several cancer-associated viruses have been shown to down-regulate TLR9 expression through their oncoproteins." (PMID 25101078, 2014). "In this study, we performed a meta-analysis to explore the association between TLR9 polymorphisms and cancer risk among 14,091 subjects." (PMID 23990988, 2013). "Secondly, subgroups analysis by ethnicity, cancer types and sample size provided better knowledge about TLR9 polymorphisms and cancer risk." (PMID 23990988, 2013). "Allele comparison and genetic models comparison were used to evaluate the cancer risk with TLR9 polymorphisms." (PMID 23990988, 2013). "Summary odds ratios (OR) and corresponding 95% confidence intervals (CIs) for polymorphisms in TLR9 and cancer risk were estimated." (PMID 23990988, 2013). "First, most of the enrolled studies only included the association of TLR9 polymorphisms with cancer risk and a more precise adjusted OR for other covariates like age, family history, infect condition and environmental factors were unavailable." (PMID 23990988, 2013). "Growing evidence suggests that mutations of TLR2/TLR9 gene are associated with the progress of cancers." (PMID 22309608, 2012). "So far, the association between TLR9 and clinopathological parameters and the survival of cancer patient has been evaluated in only a few studies." (PMID 21929816, 2011). "Similarly, TLR9 overexpression has been associated with increased inflammatory responses and poor prognosis in various cancers, including glioblastoma, prostate carcinoma, breast cancer, ovarian cancer, colorectal carcinoma, and HCC." (PMID 40495154, 2025). "Finally, specific TLR9 polymorphisms have been implicated in breast cancer susceptibility, suggesting a genetic influence on TLR9 expression and its role in cancer development." (PMID 39123407, 2024). "Previous research has linked TLR4 and TLR9 activation to cancer growth in a variety of situations." (PMID 38476365, 2024). "Messaritacis et al28 hypothesized that the presence of TLR2, TLR4, and TLR9 variants affected gut homeostasis resulting in impairment of TLRs activation, thus leading to inflammation and cancer development and progression." (PMID 37404119, 2023). "TLR9 has been linked to myeloid-derived suppressor cell (MDSC) activity in several cancers." (PMID 38260202, 2023). "However, chronic TLR-9 activation can lead to persistent inflammation, a known risk factor for cancer development, including GC." (PMID 37894471, 2023). "Finally, we demonstrated that the cancer-associated human papillomaviruses show a reduction in CpG dinucleotides within a TLR9 recognition complex." (PMID 35311536, 2022). "Various studies have underlined the antitumoral function of TLR9 in cancer." (PMID 34573939, 2021).
cancer (continued). "The involvement of TLR9 could be used as a risk stratification factor to categorize the cancer patient's prognosis and outcome; however, based on the type of cancer, it may be either attributed to the good or attributed to the poor prognosis." (PMID 33336901, 2021). "Interestingly, this study also found that combining the TLR7 knockout with TLR3 and TLR9 knockouts lead to the spontaneous emergence of cancer in the triple-TLR-deficient mice, suggesting a role for TLR3 and 9 in cancer immuno-surveillance." (PMID 33202596, 2020). "Thus, TLR9 polymorphism studies are warranted further in other autoimmune and infectious diseases along with cancers." (PMID 33643304, 2020). "Additionally, the authors underlined that the H. pylori cancer-associated cag type IV secretion system (T4SS) is mandatory for the activation of TLR9 and that the H. pylori DNA is actively translocated by this system to engage this host receptor." (PMID 30863783, 2019). "Stage-wise analysis revealed TLR9 rs187084 and rs352140 to be associated with early-stage cancer." (PMID 31278284, 2019). "We and others share evidences suggesting that loss of TLR9 expression may lead to a poor immune response in viral related cancers." (PMID 27454079, 2016). "Thus, we performed this meta-analysis with accumulated data to evaluate the overall cancer risk of selected three SNPs in TLR9 and to quantify heterogeneity between the individual studies as well as to investigate the existence of potential publication bias." (PMID 23990988, 2013). "In conclusion, our meta-analysis indicated that TLR9 rs352140 was associated with increased cancer risk, especially in Caucasians, suggested that polymorphisms in TLR9 may play a role in cancer development." (PMID 23990988, 2013). "These meta-analysis results indicate that polymorphisms in TLR9 may play a role in cancer development." (PMID 23990988, 2013). "Likewise, hypomethylation associated with cancer and aging may produce immunogenic DNA fragments—such as microsatellite or retroelement DNA—that stimulate immune responses via TLR9." (PMID 40981069, 2025). "Additionally, the TME score analysis demonstrates that the association between TLR9 and many types of cancer exhibits a range of features, including positive correlation, negative correlation, and irrelevance, but the positive correlation is the predominant finding." (PMID 35801728, 2022). "Furthermore, TLR9 expression is associated with unfavorable prognosis in several cancers including squamous cell carcinoma of the tongue, esophageal adenocarcinoma and prostate cancer and with a favorable prognosis in renal cell carcinoma and in triple-negative breast cancer." (PMID 34884547, 2021). "Also, our finding that TLR9 deficient mice fail to induce effective antitumor immune response following chemotherapy provides a potential explanation for the variations of the immune adjuvanting effects of cancer chemotherapy observed in the clinical settings." (PMID 31619293, 2019). "In conclusion, we succeeded in the development of a carrier for the anti-cancer DNA vaccine, which has dual function in DNA vaccines: an efficient gene carrier for the antigen-encoding pDNA and as an adjuvant triggered by the cytoplasmic delivery of pDNA via a TLR9-independent mechanism." (PMID 25605799, 2015). "Considering a single study might underpowered to detect the overall effects in complex diseases, a quantitative synthesis of the accumulated data from different studies was deemed important to provide evidence on the association of variants in TLR9 with cancer risk." (PMID 23990988, 2013). "While TLR9 activation by CpG ODN has shown therapeutic promise in cancer immunotherapy and antimicrobial defense, its functional outcomes exhibit striking context-dependency, influenced by factors including ODN class, target cell type, and disease milieu." (PMID 40855408, 2025).
cancer (continued). "LXR agonists synergize with sHDL nanodiscs by increasing the expression of the ABCA1 cholesterol CpG oligonucleotides are established adjuvants used in cancer immunotherapy that work through the toll-like receptor 9 pathway." (PMID 40236100, 2025). "CQ has been shown to inhibit the TLR9/nuclear factor kappa B signaling pathway, thereby reducing cancer invasiveness, and both CQ and HCQ can suppress cancer cell proliferation by interfering with the CXCL12/CXCR4 signaling pathway." (PMID 40805187, 2025). "Beyond CpG-7909, several other TLR9 agonists are under clinical investigation for cancer therapy, including MGN1703 (Lefitolimod), IMO-2125 (Tilsotolimod), SD-101, and CMP-001." (PMID 40495154, 2025). "EGFR inhibitors, often used clinically to treat cancer, block TLR9 signaling in vitro and protect mice from TLR9-induced hepatotoxicity." (PMID 40980882, 2025). "In cancer cells, DRP1-mediated mitochondrial fission induces cytosolic mtDNA stress to enhance the CCL2 secretion from cancer cells via the TLR9-mediated NF-κB signaling pathway, which promotes M2 polarization." (PMID 41373022, 2025). "As a result, research has shifted towards modifying the structure of TLR9 agonists to enhance their immune-stimulatory properties, and exploring their use in combination therapies with existing cancer treatments." (PMID 40495154, 2025). "High TLR9 expression in most human tumors, cancer cell growth, invasion, survival, and metastasis are important factors." (PMID 38685971, 2024). "Downstream pathways that become upregulated by TLR2 and TLR9 result in increased inflammatory signaling, which was suggested to support cancer progression over time." (PMID 38390872, 2024). "In HPV-related cancer vaccine research, combining TLR9 agonist CpG with liposomes significantly enhanced vaccine immune responses and protective efficacy." (PMID 39206192, 2024). "Given the current efforts to leverage the TLR9 agonist CpG-ODN in cancer therapy, we investigated its potential for therapy in LAM." (PMID 36798234, 2024). "The involvement of TLR9 in promoting inflammation and enhancing invasive capacities highlights the intricate interplay between the immune system and cancer progression." (PMID 39123407, 2024). "Unmethylated CpG-ODN were shown to induce the activation of Toll-like receptor 9 (TLR9), enhancing the antigen presentation and improving the immune profile of several cancers, including GBM." (PMID 38792022, 2024). "TLR9 is an innate immune system DNA receptor, which is widely expressed in breast and other cancers." (PMID 39644451, 2024). "For instance, TLR7 and TLR9 are often activated in therapies against viral infections and as adjuvants in cancer vaccines, while TLR2 and TLR4 are targeted by antagonists to mitigate inflammatory responses in sepsis and other inflammatory diseases." (PMID 38732254, 2024). "Several new adjuvants, including TLR3, TLR7, and TLR9 agonists, are undergoing clinical trials to enhance the efficacy of immune checkpoint inhibitors and improve cancer vaccine responses." (PMID 39206192, 2024). "TLR9 agonists hold great potential in cancer therapy, showing the synergistically enhanced immunostimulatory capacity when used in combination with other agents, chemotherapy, radiation, or checkpoint inhibitors." (PMID 38850110, 2024). "Activated TLR9 has been shown to play a role in the invasion and metastasis of cancer cells in vitro." (PMID 39123407, 2024). "Herein, we discovered a novel function and mechanism of TLR9 activation, which increased PS exposure in cancer cells." (PMID 37324949, 2023). "Similar to cGAS, TLR9 can recognize RNA:DNA hybrids, and activating TLR9 has demonstrated potential as a novel immunotherapeutic approach to improve classic cancer therapies." (PMID 37138342, 2023). "When grouped by GC attributes, key relationships emerged between TLR-9 amounts, the histological grade, progression stages, and cancer types." (PMID 37894471, 2023).
cancer (continued). "The association between TLR9-rs352140 SNP and cell death responses of BL cells highlights its potency as a biological marker and an anti-cancer agent (synthetic TLR9 agonists)." (PMID 37822929, 2023). "It has also been shown that mouse neutrophil-derived NETs trigger HMGB1 release and activate TLR9-dependent pathways in cancer cells to promote their adhesion, proliferation, migration and invasion." (PMID 36788538, 2023). "Apart from their immune regulatory effect, the direct effect of TLR9 agonists on cancer cells with TLR9 expression cannot be ignored." (PMID 36765389, 2023). "Previously, different SNPs in the TLR9 gene were well-established with infectious diseases and cancers." (PMID 37998038, 2023). "MNs are synthesized from cross-linked hyaluronic acid (HA) and loaded with drug CpG oligonucleotide (TLR9 agonist) containing model immune regulation nanoparticles for cancer treatment in melanoma and cancer models." (PMID 37896303, 2023). "TLR9’s function in tumorigenesis is also a double-edged sword, and although it has a potential anti-cancer capacity, a pro-tumorigenic relevance is more likely." (PMID 36611945, 2022). "In vitro studies have shown that NETs induced changes in the inflammatory microenvironment and activated TLR9-dependent pathways in cancer cells by releasing HMGB1, thereby promoting cancer cell adhesion, proliferation, migration and invasion." (PMID 36365233, 2022). "TLR9 agonists have been extensively evaluated preclinically and clinically as agents for treating cancers, asthma and allergies, infectious diseases, and as vaccine adjuvants." (PMID 36582243, 2022). "TLR9-induced immune activation has been extensively characterized in preclinical and clinical studies of cancer." (PMID 36582243, 2022). "Although it is in the early clinical development, the agonists of TLR9 have demonstrated potential for cancer treatment." (PMID 39871923, 2022). "The safety and PD results of this study are compelling support for the use of TLR9-agonist cavrotolimod with CPIs in populations with advanced cancer." (PMID 36582243, 2022). "CRISPR Cas9 invalidation of TLR9 impedes CXCL10 production by cancer cells, T cells recruitment and antitumor effect of chemoimmunotherapy plus MEK inhibitor." (PMID 35529902, 2022). "In the mechanistic investigations in vitro, NETosis triggered the release of HMGB1 and activated TLR9 pathways in cancer cells, further promoting tumor progression." (PMID 34712384, 2021). "It has been shown that ccfDNA is recognized by the Toll-Iike Receptor 9 (TLR9) and contributes to cancer progression." (PMID 33578793, 2021). "For example, phosphorothioation potentiates TLR9 activation by the CpG agonists, which are being explored as vaccine adjuvants and in cancer therapy." (PMID 33531504, 2021). "It is a key inhibitor of TLR9 and is used in the treatment of cancer, especially for its anti-HCC effect, often combined with conventional anticancer drugs." (PMID 34203465, 2021). "By utilizing TLR9 siRNAs, our previous research has shown that silencing TLR9 in MDA-MB-231 cells enhanced cancer cell viability and their invasive capability under hypoxia." (PMID 34479492, 2021). "Here we investigated if suppressed TLR9 can influence cancer cell-secreted soluble mediators repertoire and consequently the MΦ polarization under hypoxic conditions." (PMID 34479492, 2021). "Cell-free DNA (cf-DNA) derived from cancer cells can activate TLR9 signaling and promote IL-8 secretion in CRC." (PMID 34712384, 2021). "Further studies showed that NETs activated the Toll-like receptor 9 (TLR9) signaling pathway in cancer cells by releasing highly mobile group box 1 (HMGB1) proteins." (PMID 34116679, 2021). "Targeting the TLR-9-MyD88 pathway is also used to regulate adaptive immune responses, but the majority of studies were focused on cancer." (PMID 32934605, 2020). "Although TLRs are involved in the immune response, TLR2, TLR4, and TLR9 contribute to cancer proliferation and progression." (PMID 32380783, 2020).
cancer (continued). "In the following discussion, we will focus on advances in the use of CpG-oligodeoxynucleotide (CpG-ODN), a synthetic TLR9 agonist to increase the efficacy of cancer immunotherapy with checkpoint blockade." (PMID 32547560, 2020). "Toll-like receptor 4 (TLR4) and TLR9 agonists have been shown to decrease cancer metastasis by increasing NK cell cytotoxicity during the perioperative period." (PMID 33353113, 2020). "Current clinical trials of combination cancer immunotherapies using a TLR9 activation agonist and a checkpoint blockade agent." (PMID 32547560, 2020). "As outlined in the previous section, not only does HMGB1 bind platelets via TLR4, it also activates TLR9-dependent pathways in cancer cells, thereby promoting tumor cell proliferation, adhesion, migration and invasion after surgical stress." (PMID 33353113, 2020). "This review first describes the underlying mechanisms of action and current status of monotherapy using TLR9 agonists and immune checkpoint inhibitors for cancer immunotherapy." (PMID 32547560, 2020). "TLR9‐mediated NF‐κB signalling is required for cancer cell migration and proliferation in gastric cancer cell models, which is inhibited by CQ." (PMID 32715647, 2020). "TLR9 is expressed in many cancer tissues and cell lines, including gastric, hepatocellular, prostate, and colorectal cancers." (PMID 33469538, 2020). "We provide the evidence that Lon overexpression promotes the inflammation by the cytosolic mtDNA-activated STING-TBK1 pathway in cancer cells and the TLR9 pathway in macrophages in the TME." (PMID 33268351, 2020). "Specifically, cancer nano-vaccines co-deliver peptides and TLR9 agonists, and gold nanoparticles the anionic TLR3 agonist poly I:C co-delivered with cationic antigen peptides." (PMID 33679703, 2020). "Mechanistically, these ADV-induced GSCs upregulated lncRNA NEAT1, which is downstream to TLR9 and plays important roles in cancer stem cells likely via strengthening STAT3." (PMID 32843056, 2020). "The majority of the preclinical work concerning TLR9 agonists have similarly been conducted in the field of cancer treatment and is thus beyond the scope of this review but has been described elsewhere." (PMID 32595636, 2020). "In the liver, TLR4 and TLR9 play essential roles in the liver inflammation–fibrosis–cancer axis, as TLR4–/– or TLR9–/–Tak1ΔHep mice experience reduced spontaneous HCC development compared to Tak1ΔHep mice." (PMID 33163393, 2020). "There is a large body of preclinical data and early human clinical trial results showing the safety and therapeutic potential of TLR9 modulating compounds to improve vaccines and treat cancer, infectious disease, allergy/asthma, autoimmune disorders." (PMID 33519463, 2020). "Toll-like receptor 9 is a key innate immune receptor involved in detecting infectious diseases and cancer." (PMID 31856726, 2019). "Both TLR4 agonist GLA-SE and TLR9 agonist CpG-C oligodeoxynucleotides significantly decrease cancer metastasis by increasing NK cell cytotoxicity during the perioperative period in a mouse model without adverse effects." (PMID 31477121, 2019). "Within cases, TLR9 rs187084 showed over presentation in early-stage cancer compared with late stages." (PMID 31278284, 2019). "Activation of other TLRs, such as TLR2, TLR5, TLR7, TLR8 and TLR9, has been reported to enhance proliferation in various cancers including liver, gastric, lung, and breast cancer." (PMID 31480568, 2019). "Synthetic TLR9-active ODNs have shown utility as vaccine adjuvants and anti-cancer immunotherapeutic agents." (PMID 31856726, 2019). "Other TLR9 agonists with a similar chemical composition soon followed suit especially for application to cancer treatment." (PMID 30621769, 2019). "Therapeutic targeting of TLR9 has proven to be efficient in pre-clinical models of various cancers including BC and many drugs are currently being tested in several cancer types, some of them even reaching phase III (NCT03445533)." (PMID 31060337, 2019).